ABCA4 (ATP binding cassette subfamily A member 4)
Description:
Flippase that catalyzes in an ATP-dependent manner the transport of retinal-phosphatidylethanolamine conjugates like 11-cis and all-trans isomers of N-retinylidene-phosphatidylethanolamine (N-Ret-PE) from the lumen to the cytoplasmic leaflet of photoreceptor outer segment disk membranes, where 11-cis-retinylidene-phosphatidylethanolamine is then isomerized to its all-trans isomer and reduced by RDH8 to produce all-trans-retinol. This transport activity ensures that all-trans-retinal generated from photoexcitation and 11-cis-retinal not needed for the regeneration of rhodopsin and cone opsins are effectively cleared from the photoreceptors, therefore preventing their accumulation and the formation of toxic bisretinoid. Displays ATPase activity in vitro in absence of retinal substrate. May display GTPase activity that is strongly influenced by the lipid environment and the presence of retinoid compounds. Binds the unprotonated form of N-retinylidene-phosphatidylethanolamine with high affinity in the absence of ATP, and ATP binding and hydrolysis induce a protein conformational change that causes N-retinylidene-phosphatidylethanolamine release (By similarity).
Synonyms: RmP; ABCR; FFM; ARMD2; CORD3; ABC10; RP19; STGD; STGD1
Tractability: Small molecule: a structure with a bound ligand is known; it belongs to a druggable protein family. Antibody: UniProt predicts a signal peptide or a membrane-spanning region; its Gene Ontology location is reachable by antibodies, with medium confidence.
Gene: Protein-coding gene on chromosome 1 (93,992,834 to 94,121,148, reverse strand). Ensembl gene ENSG00000198691.
Subcellular location: Membrane; Endoplasmic reticulum; Cytoplasmic vesicle; Cell projection, cilium, photoreceptor outer segment
Subcellular location (Human Protein Atlas): Endoplasmic reticulum
Pathways (Reactome):
Disease: Defective visual phototransduction due to ABCA4 loss of function
Sensory Perception: The canonical retinoid cycle in rods (twilight vision)
Transport of small molecules: ABC-family protein mediated transport
Gene Ontology:
Molecular function: 11-cis retinal binding; all-trans retinal binding; ATP hydrolysis activity; ATPase-coupled intramembrane lipid transporter activity; flippase activity; N-retinylidene-phosphatidylethanolamine flippase activity; phosphatidylethanolamine flippase activity; ATP binding; ATPase-coupled transmembrane transporter activity; GTPase activity; retinoid binding; retinol transmembrane transporter activity; ABC-type transporter activity
Biological process: phospholipid translocation; retinal metabolic process; phototransduction, visible light; retinoid metabolic process; transmembrane transport; visual perception; lipid transport; organic hydroxy compound transport; retinol transport
Cellular component: cytoplasmic vesicle; endoplasmic reticulum; membrane; photoreceptor disc membrane; photoreceptor outer segment; rod photoreceptor disc membrane; plasma membrane
Genetic constraint (gnomAD): Loss-of-function variants: 190 observed, 272.62 expected, observed/expected ratio (o/e) 0.7, 90% interval 0.62 to 0.79. The upper end of that interval is the gene's LOEUF score, 0.79, which puts it in group 3 of 6, group 1 being the genes least tolerant of losing a copy. Missense variants: 2,771 observed, 2,977.4 expected, observed/expected ratio (o/e) 0.93, 90% interval 0.9 to 0.96. Synonymous variants: 1,126 observed, 1,146.1 expected, observed/expected ratio (o/e) 0.98, 90% interval 0.94 to 1.03.
Gene-disease validity (ClinGen):
ClinGen rates the evidence that ABCA4 causes each of these diseases.
ABCA4-related retinopathy (autosomal recessive): Definitive. An inherited retinopathy caused by bi-allelic variants in the ABCA4 gene.
age related macular degeneration 2 (autosomal dominant): Disputed.
Homologues: Orthologues: chimpanzee ABCA4 (99% identical), macaque ABCA4 (98% identical), dog ABCA4 (90% identical), guinea pig ABCA4 (89% identical), mouse Abca4 (88% identical), rat Arhgap29 (88% identical), pig ABCA4 (86% identical), rabbit ABCA4 (85% identical), tropical clawed frog abca4 (69% identical), zebrafish abca4b (65% identical), zebrafish abca4a (64% identical), Caenorhabditis elegans abt-2 (27% identical), and 11 more. Paralogues in human: ABCA1 (50% identical), ABCA7 (43% identical), ABCA2 (38% identical), ABCA13 (31% identical), ABCA12 (31% identical), ABCA3 (27% identical), ABCA9 (19% identical), ABCA5 (19% identical), ABCA6 (19% identical), ABCA8 (18% identical), ABCA10 (17% identical).
Diseases named in the same sentence as ABCA4 in open-access papers:
ABCA4 is named in the same sentence as 182 diseases in open-access papers, as found by Europe PMC text mining. Sharing a sentence is not in itself a finding about the gene and the disease. The quoted sentences say what the papers report.
Stargardt disease (301 papers, 2005 to 2026). "The ABCA4 gene is classically associated with Stargardt disease, a juvenile‐onset macular dystrophy where central vision is primarily affected." (PMID 41458191, 2026). "Six carrier couples (4%) were identified as being at reproductive risk of non-syndromic hearing loss (GJB2, 2 couples), cystic fibrosis (CFTR), Stargardt disease and retinitis pigmentosa (ABCA4), Smith-Lemli-Opitz syndrome (DHCR7), and Fabry disease (GLA)." (PMID 42071123, 2026). "In this study, we employed hiPSCs derived from patients with Stargardt disease or Best disease, carrying pathogenic variants in ABCA4 or BEST1, respectively, to explore gene editing in human models." (PMID 41827889, 2026). "The mutational spectrum associated with ABCA4 retinopathies includes Stargardt disease, cone‐rod dystrophy, and retinitis pigmentosa, and in several large cohort studies, the ABCA4 gene is one of the most common causes of hereditary retinal dystrophies." (PMID 41458191, 2026). "AlphaMissense underperformed in predicting hypomorphic variants, particularly in ABCA4-associated Stargardt disease." (PMID 41492285, 2026). "An illustrative example is a 23-year-old female with bull’s eye maculopathy that was consistent with a milder late-onset macular disease compared with classic forms of ABCA4-associated Stargardt disease." (PMID 41492285, 2026). "The ABCA4 gene is associated with a wide spectrum of retinopathies, most commonly Stargardt disease, which is characterized by central macular degeneration." (PMID 41458191, 2026). "Significant progress has been made in recent years, furthering the understanding of ABCA4 variants and their contribution to Stargardt disease." (PMID 40960229, 2025). "Despite ABCA4 mutations being the chief contributor in the etiology of Stargardt’s disease, gene therapies supplementing the wildtype ABCA4 are limited." (PMID 40725253, 2025). "Using this approach, they achieved successful excision of an intronic region of ABCA4 harboring deep intronic pathogenic variants causing Stargardt disease." (PMID 41036464, 2025). "Functional efficacy is validated using preclinical models such as rd10 mice (a model of RP) and ABCA4-deficient mice (Stargardt disease), where optokinetic response testing assesses visual acuity and ERG measures photoreceptor function." (PMID 40143072, 2025). "Stargardt disease (juvenile macular dystrophy) is an autosomal recessive disorder caused by mutations in the ABCA4 gene, leading to lipofuscin accumulation in the RPE and progressive macular atrophy." (PMID 40806887, 2025). "Often brought on by mutations in the ABCA4 gene, Stargardt disease (STGD) is the most common hereditary retinal disease." (PMID 40725503, 2025). "Stargardt disease was first described in 1909 by Dr. Karl Stargardt, but its genetic basis was identified only in 1997 with the discovery of ABCA4 mutations." (PMID 40725253, 2025). "This present article will concentrate on the current state of research in ABCA4-associated Stargardt disease as this is where the majority of research is currently focused." (PMID 40960229, 2025). "Pathogenic variants in the ABCA4 gene are a significant cause of AR cone-rod dystrophy, accounting for 30 to 60% of cases, including Stargardt disease." (PMID 41465088, 2025). "The biallelic ABCA4 variants cause a group of ABCA4-related retinopathies, including Stargardt disease (STGD1), cone–rod dystrophy (CRD), retinitis pigmentosa, generalized choriocapillaris dystrophy, and rapid onset chorioretinopathy." (PMID 40244202, 2025). "Stargardt’s disease (STGD1) is an autosomal recessive juvenile macular degeneration caused by mutations in the ABCA4 gene, impairing clearance of toxic retinoid byproducts in the retinal pigment epithelium (RPE)." (PMID 40725253, 2025).
Stargardt disease (continued). "ABCA4 has established roles in retinal pathology, with mutations causing Stargardt disease through impaired clearance of toxic retinal aldehydes, leading to lipofuscin accumulation and retinal degeneration." (PMID 41010507, 2025). "Stargardt disease, caused by pathogenic variants in the ABCA4 gene, was the most frequently reported gene in our cohort." (PMID 41465088, 2025). "Various studies have reported deep intronic variants in patients with Stargardt’s disease with frequency ranging from 2% to 18% in the ABCA4 gene." (PMID 40725253, 2025). "Numerous mutations in the ABCA4 gene have been associated with the Stargardt’ disease, highlighting the genetic heterogeneity which translates into the heterogeneity of disease onset and progression." (PMID 40725253, 2025). "Stargardt disease is an autosomal recessive retinal dystrophy caused by biallelic variants in ABCA4, which encodes an ATP-binding cassette transporter that plays a crucial role in the visual cycle." (PMID 40710345, 2025). "Mutations in ABCA4, typically associated with Stargardt disease, have also been implicated in specific AMD subtypes." (PMID 41516080, 2025). "ABCA4 gene mutations, comprising Stargardt disease, present with peripapillary sparing, which is useful information to discern MIDD." (PMID 41303269, 2025). "The variant, when present in trans with a loss-of-function ABCA4 variant, was associated with late symptom onset and foveal sparring Stargardt’s disease." (PMID 40725253, 2025). "Mutations in the ABCA4 gene, located on chromosome 1, are the primary cause of Stargardt disease, which follows an autosomal recessive inheritance pattern." (PMID 40244202, 2025). "In a German multicenter cohort study of 335 patients with Stargardt’s disease, 148 mutations in the ABCA4 gene that are likely to impact disease pathology have been identified." (PMID 40725253, 2025). "The clinical diagnosis of Stargardt disease in P23 was supported by genetic testing, which revealed one mild and one severe ABCA4 allele." (PMID 41234456, 2025). "A heterozygous c.286A>G (p.Asn96Asp) variant was identified in ABCA4 (NM_000350.3), a gene associated with Stargardt disease 1, a recessive macular dystrophy." (PMID 40282387, 2025). "A discrepancy between the genetic prevalence of ABCA4 variants and the observed phenotypic prevalence of Stargardt disease has been noted." (PMID 40960229, 2025). "In this study, we aimed to identify and analyze potential pathogenic ABCA4 variants in patients with Stargardt disease or retinitis pigmentosa and to explore the impact of an intronic variant (NM_000350.3:c.6386 + 4A>G) on mRNA splicing." (PMID 40606666, 2025). "As per a comprehensive study published in November 2023, 796 pathogenic, 452 likely pathogenic, and 971 ABCA4 variants of uncertain significance were identified associated with Stargardt’s disease." (PMID 40725253, 2025). "Our study identified two novel ABCA4 variants, expanding the mutational spectrum of the ABCA4 gene in Stargardt disease and retinitis pigmentosa while providing new insights into the molecular pathology of ABCA4 splicing defects." (PMID 40606666, 2025). "Genetic testing confirmed two biallelic pathogenic variants in the ABCA4 gene, validating the diagnosis of Stargardt disease." (PMID 39991341, 2025). "Stargardt disease, which is the most common hereditary retinal disease, is most often the result of mutations in the ABCA4 gene." (PMID 41440982, 2025). "A total of 353 deep intronic variants in ABCA4 gene have been identified in patients with Stargardt’s disease." (PMID 40725253, 2025). "Mutations in ABCA4 are the major cause of Stargardt disease and a subset of cone-rod dystrophy with progressive blindness in children and young adults." (PMID 38500685, 2024). "In one study, a CEP was developed and validated to measure disease progression in ABCA4-associated Stargardt disease." (PMID 39336999, 2024).
Stargardt disease (continued). "The intronic ABCA4 c.5461-10T > C variant, frequently seen in patients with Stargardt disease, causes splice defects and reduced ABCA4 protein level." (PMID 39011458, 2024). "We report a novel pathogenic complex deep-intronic allele in ABCA4 intron 11 (NM_000350.2:c.[1555-5882C>A;1555-5784C>G]) identified in a patient affected by childhood-onset Stargardt disease." (PMID 39766771, 2024). "Background/Objectives: Stargardt disease (STGD1) is an autosomal recessive disorder caused by pathogenic variants in ABCA4 that affects the retina and is characterised by progressive central vision loss." (PMID 39766771, 2024). "Specifically, the most frequently mutated gene in Usher syndrome, MYO7A (7 kb), and in Stargardt disease, ABCA4 (128 kb), exceed the carrying capacity of AAVs." (PMID 39064263, 2024). "The discrepancy for reporting in favor of ABC was even greater for the periodic fever-associated TNFRSF1A(NM_001065.4) c.362G > A, p.(Arg121Gln) variant (81% vs 64%) and the Stargardt disease-associated ABCA4 Arg1868Ile variant (86% vs 67%)." (PMID 38778080, 2024). "Deep-intronic (DI) variants represent approximately 10%–12% of disease-causing genetic defects in ABCA4-associated Stargardt disease (STGD1)." (PMID 39494150, 2024). "USH2A-associated retinal pathology is the third most common autosomal recessive form of IRD among Russian patients, after Stargardt disease, caused by biallelic variants in the ABCA4 gene and achromatopsia, associated with mutations in the CNGB3 gene." (PMID 39596236, 2024). "Recently, the three-year safety results of the EIAV-ABCA4 gene therapy trial in ABCA4-associated Stargardt disease patients showed that this therapy is relatively well tolerated." (PMID 38391665, 2024). "To determine the efficacy of the VLP platform for studying ABCA4 variants, we examined two known Stargardt disease–associated pathogenic ABCA4 variants, p.N965S and p.C1488R, in the VLP platform." (PMID 39222682, 2024). "Antisense oligonucleotides rescue aberrant splicing caused by an ultrarare ABCA4 variant in children with early-onset Stargardt disease." (PMID 39138523, 2024). "We show this in an adolescent with early-onset ABCA4-related Stargardt disease (subject 15) who harbors the known pathogenic variant c.5461-10T>C noted in the previous individual." (PMID 39264853, 2024). "Over 1500 missense mutations in ABCA4, many in the nucleotide-binding domains (NBDs), have been genetically linked to Stargardt disease." (PMID 39128720, 2024). "In Stargardt disease, mutations in the ABCA4 gene disrupt the normal function of RPE cells through several mechanisms." (PMID 39201545, 2024). "Treatment for patients with ABCA4-associated Stargardt disease is conducted with an equine infectious anemia virus-driven vector (EIAV-ABCA4)." (PMID 39138523, 2024). "The other IRD group included Stargardt's disease carrying ABCA4 variants, as well as individuals with Cone-Rod Dystrophy (CORD) or RP presenting with various genetic variants such as RDH12, RPGR, LCA5,CEP290, RP2, USH2A, and EYS." (PMID 38466290, 2024). "Both allelic and symptomatic heterogeneity is a characteristic aspect of ABCA4-associated Stargardt disease (STGD1, OMIM: 248200)." (PMID 38607040, 2024). "Collectively, our studies provide insight into the structure and function of ABCA4 and mechanisms underlying Stargardt disease." (PMID 39128720, 2024). "Roberts successfully used tests developed based on common ABCA4 mutations to diagnose Stargardt macular dystrophy, which links the disease to the mutations." (PMID 36836473, 2023). "For this, we focused on the Abca4-deficient (Abca4-/-) mouse model for Stargardt disease, which represents the most common inherited macular degeneration." (PMID 37852949, 2023). "The variants in the ABCA4 gene cause aberrant splicing that results in defects characterizing Stargardt disease." (PMID 36836473, 2023).